ZNF672 (zinc finger protein 672)
Description:
May be involved in transcriptional regulation.
Synonyms: FLJ22301
Tractability: PROTAC: ubiquitination databases record sites on it.
Gene: Protein-coding gene on chromosome 1 (248,838,210 to 248,849,520, forward strand). Ensembl gene ENSG00000171161.
Subcellular location: Nucleus
Subcellular location (Human Protein Atlas): Nucleoplasm
Gene Ontology:
Molecular function: protein binding; DNA-binding transcription factor activity, RNA polymerase II-specific; sequence-specific DNA binding
Biological process: regulation of transcription by RNA polymerase II
Cellular component: nucleoplasm; nucleus
Genetic constraint (gnomAD): Missense variants: 733 observed, 592.57 expected, observed/expected ratio (o/e) 1.24, 90% interval 1.16 to 1.32. Synonymous variants: 358 observed, 260.86 expected, observed/expected ratio (o/e) 1.37, 90% interval 1.26 to 1.5.
Homologues: Orthologues: chimpanzee ZNF672 (99% identical), macaque ZNF672 (98% identical), pig ZNF672 (82% identical), rat Zfp672 (78% identical), mouse Zfp672 (78% identical), zebrafish si:dkey-14k9.3 (24% identical), tropical clawed frog znf205 (16% identical). Paralogues in human: ZNF250 (37% identical), ZNF436 (36% identical), ZNF835 (36% identical), ZNF33B (36% identical), ZNF724 (36% identical), ZNF182 (36% identical), ZNF229 (36% identical), ZNF658 (36% identical), ZNF678 (36% identical), ZNF879 (36% identical), ZNF16 (36% identical), ZNF726 (36% identical), and 164 more.
Diseases named in the same sentence as ZNF672 in open-access papers:
ZNF672 is named in the same sentence as 4 diseases in open-access papers, as found by Europe PMC text mining. Sharing a sentence is not in itself a finding about the gene and the disease. The quoted sentences say what the papers report.
adenomyosis (1 paper, 2019). The growth of endometrial tissue inside the muscular wall of the uterine corpus. "Some mutations were shared among almost all multi-regional samples from a single patient (e.g., ZNF672 in Patient #28; C1QTNF and MSS51 in Patient #29), suggesting that these genetic alterations were acquired early during adenomyosis development, whereas other mutations were more restricted." (PMID 31857578, 2019).
ZNF672 also shares sentences with these, for which no sentence is quoted: breast carcinoma (1 paper); gastric cancer (1); ovarian carcinoma (1).